BCR (BCR activator of RhoGEF and GTPase)
Description:
Protein with a unique structure having two opposing regulatory activities toward small GTP-binding proteins. The C-terminus is a GTPase-activating protein (GAP) domain which stimulates GTP hydrolysis by RAC1, RAC2 and CDC42. Accelerates the intrinsic rate of GTP hydrolysis of RAC1 or CDC42, leading to down-regulation of the active GTP-bound form. The central Dbl homology (DH) domain functions as guanine nucleotide exchange factor (GEF) that modulates the GTPases CDC42, RHOA and RAC1. Promotes the conversion of CDC42, RHOA and RAC1 from the GDP-bound to the GTP-bound form. The amino terminus contains an intrinsic kinase activity. Functions as an important negative regulator of neuronal RAC1 activity (By similarity). Regulates macrophage functions such as CSF1-directed motility and phagocytosis through the modulation of RAC1 activity. Plays a major role as a RHOA GEF in keratinocytes being involved in focal adhesion formation and keratinocyte differentiation.
Synonyms: BCR1; D22S11; D22S662; CML; PHL; ALL
Tractability: Small molecule: an approved drug acts on it; a structure with a bound ligand is known; a high-quality ligand is known; it belongs to a druggable protein family. Antibody: its Gene Ontology location is reachable by antibodies, with medium confidence; the Human Protein Atlas places it where antibodies can reach. PROTAC: ubiquitination databases record sites on it; its protein half-life has been measured; a small molecule that binds it is known.
Target class: Other cytosolic protein
Chemical probes: CAY10717, PD134585, PD134586, PD134587, PD134588, PD134589, PD134590, PD134591, PD134592, PD134593, PD134594, PD134595, PD134596, PD134597, PD134598, PD134600, PD134601, PD134603, PD134604, PD134605, and 2 more
Gene: Protein-coding gene on chromosome 22 (23,179,704 to 23,318,037, forward strand). Ensembl gene ENSG00000186716.
Subcellular location: Postsynaptic density; Cell projection, dendritic spine; Cell projection, axon; Synapse
Subcellular location (Human Protein Atlas): Cytosol; Plasma membrane; Nucleoplasm
Pathways (Reactome):
Signal Transduction: CDC42 GTPase cycle; RAC1 GTPase cycle; RAC2 GTPase cycle; RAC3 GTPase cycle; RHOA GTPase cycle; RHOB GTPase cycle; RHOC GTPase cycle
Disease: Signaling by FGFR1 in disease; Signaling by cytosolic FGFR1 fusion mutants
Gene Ontology:
Molecular function: GTPase activator activity; guanyl-nucleotide exchange factor activity; protein binding; protein serine kinase activity; protein serine/threonine kinase activity; protein tyrosine kinase activity
Biological process: activation of GTPase activity; focal adhesion assembly; keratinocyte differentiation; regulation of Rho protein signal transduction; small GTPase-mediated signal transduction; modulation of chemical synaptic transmission; protein phosphorylation; regulation of small GTPase mediated signal transduction; signal transduction; intracellular signal transduction; negative regulation of blood vessel remodeling; negative regulation of cellular extravasation; regulation of vascular permeability
Cellular component: extracellular exosome; membrane; protein-containing complex; cytosol; glutamatergic synapse; postsynaptic density; Schaffer collateral - CA1 synapse; synapse; axon; dendritic spine; plasma membrane
Genetic constraint (gnomAD): Loss-of-function variants: 56 observed, 115.07 expected, observed/expected ratio (o/e) 0.49, 90% interval 0.39 to 0.61. The synonymous counts are far from expectation, so gnomAD's model fits this gene poorly and the ratio says little. Missense variants: 1,575 observed, 1,555.8 expected, observed/expected ratio (o/e) 1.01, 90% interval 0.97 to 1.05. Synonymous variants: 770 observed, 656.02 expected, observed/expected ratio (o/e) 1.17, 90% interval 1.11 to 1.25.
Homologues: Orthologues: chimpanzee BCR (99% identical), macaque BCR (99% identical), dog BCR (95% identical), mouse Bcr (94% identical), rat Bcr (94% identical), pig BCR (94% identical), guinea pig BCR (90% identical), rabbit BCR (87% identical), zebrafish bcr (78% identical), zebrafish BCR (73% identical), tropical clawed frog bcr (69% identical), Drosophila melanogaster RhoGAP1A (30% identical). Paralogues in human: ABR (45% identical).
Diseases named in the same sentence as BCR in open-access papers:
BCR is named in the same sentence as 256 diseases in open-access papers, as found by Europe PMC text mining. Sharing a sentence is not in itself a finding about the gene and the disease. The quoted sentences say what the papers report.
chronic myeloid leukemia (913 papers, 2001 to 2026). "We report a 65-year-old man with FLT3 D835V-mutated acute myeloid leukemia (AML) and BCR::ABL1-positive chronic myeloid leukemia (CML) that coexisted as genetically independent clones." (PMID 41982787, 2026). "BCR::ABL1-positive is the hallmark of chronic myeloid leukemia, whereas BCR::ABL1-negative MPNs clinically manifest as polycythemia vera (PV), essential thrombocythemia (ET), or primary myelofibrosis (PMF)." (PMID 40429745, 2025). "Despite the groundbreaking success of tyrosine kinase inhibitor therapy, the management of chronic myeloid leukemia patients is often impaired by resistance due to specific point mutations in the BCR::ABL1 oncogene." (PMID 39996897, 2025). "Tyrosine kinase inhibitors (TKIs) such as imatinib, dasatinib, and nilotinib have markedly improved outcomes of patients with chronic myeloid leukemia, the majority of which is caused by the classical oncogenic fusion gene BCR-ABL." (PMID 40615663, 2025). "Chronic myeloid leukemia (CML) can be effectively treated inhibiting the disease-causing BCR::ABL1 kinase by tyrosine kinase inhibitors (TKIs)." (PMID 41035915, 2025). "BCR is classically associated with chronic myelogenous leukemia, in which it forms a fusion protein with tyrosine-protein kinase ABL1 (c-Abl) leading to aberrant kinase activity." (PMID 41035411, 2025). "Chronic myeloid leukemia (CML) harboring BCR/ABL-T315I mutation has been a challenging obstacle for targeted therapy due to the acquired resistance to tyrosine kinase inhibitor (TKI)-based therapy." (PMID 40346054, 2025). "We report the case of a 51-year-old male patient initially diagnosed with JAK2-V617F-mutated polycythemia vera (PV), who developed chronic phase BCR::ABL1-positive chronic myeloid leukemia (CML) 11 years later." (PMID 41137901, 2025). "Chronic myeloid leukemia (CML) is a myeloproliferative neoplasm driven by the fusion gene BCR::ABL1, which encodes a constitutively active and targetable tyrosine kinase." (PMID 40442861, 2025). "Missense mutations in the BCR::ABL1 kinase domain are found in approximately 12–80% of patients with chronic myeloid leukemia (CML)." (PMID 40332324, 2025). "The BCR::ABL1 fusion oncogene is not only common in ALL but represents a hallmark feature in chronic myeloid leukemia (CML)." (PMID 39966356, 2025). "For example, mutations in the BCR-ABL kinase domain have been shown to confer resistance to Imatinib in chronic myeloid leukemia (CML) by disrupting inhibitor binding and reducing therapeutic efficacy." (PMID 41144441, 2025). "BCR mutation is a key part of the pathogenesis of chronic myeloid leukemia, the BCR-ABL1 fusion (Philadelphia chromosome), where the upregulation of tyrosine kinase activity drives leukemic cell proliferation." (PMID 40860802, 2025). "The BCR::ABL1 fusion gene is not only a hallmark of chronic myeloid leukemia (CML) but is also present in a proportion of patients (3–5% in children, 20–30% in adults) with acute lymphoblastic leukemia (ALL)." (PMID 38970095, 2024). "HAP1 cells represent a near-haploid cell line engineered from cells isolated from a patient with chronic myeloid leukemia triggered by the BCR-ABL fusion mutation." (PMID 39513908, 2024). "These mutations have been extensively studied in chronic myeloid leukemia (CML) but less so in BCR::ABL1‐positive acute lymphoblastic leukemia (ALL)." (PMID 39440695, 2024). "Chronic myeloid leukemia (CML) is a myeloproliferative neoplasm caused by constitutive activation of the BCR::ABL1 tyrosine kinase." (PMID 38287132, 2024). "The ERBB2 receptor is linked to breast adenocarcinoma, the BCR/ABL fusion gene to chronic myelogenous leukemia, and BRAF (V600E) mutations to melanoma, colorectal cancer, and thyroid cancer." (PMID 39767657, 2024). "The BCR::ABL1 fusion gene is known for its association with chronic myelogenous leukemia (CML) but has also recently become its own entity in de novo acute myeloid leukemia (AML)." (PMID 38895060, 2024).
chronic myeloid leukemia (continued). "Chronic myeloid leukemia (CML) is a myeloproliferative disorder associated with a translocation that results in a BCR::ABL1 fusion gene with enhanced and deregulated tyrosine kinase activity." (PMID 38931954, 2024). "A fusion gene breakpoint cluster region (BCR)-ABL1 is commonly associated with chronic myeloid leukemia (CML) and a subset of acute lymphoblastic leukemia (ALL)." (PMID 37627077, 2023). "Chronic myeloid leukemia originates from hematopoietic stem cells acquiring the BCR-ABL fusion gene, which encodes a tyrosine kinase with consecutive activity." (PMID 38103082, 2023). "The screening of the BCR::ABL1 kinase domain (KD) mutation has become a routine analysis in case of warning/failure for chronic myeloid leukemia (CML) and B-cell precursor acute lymphoblastic leukemia (ALL) Philadelphia (Ph)-positive patients." (PMID 35906470, 2022). "Chronic myeloid leukemia (CML) is a hematopoietic malignancy defined by the BCR-ABL fusion protein encoded by the Philadelphia chromosome (Ph)." (PMID 35333695, 2022). "Chronic myeloid leukaemia (CML) is a haematopoietic malignancy caused by the presence of the fusion gene BCR-ABL in stem/progenitor cells." (PMID 35348419, 2022). "All components of the AURKA-PLK1-FOXM1 axis appear to be hyperactivated due to multiple events associated with a BCR-ABL fusion protein that promotes resistance to tyrosine kinase inhibitors in chronic myeloid leukemia (CML)." (PMID 35359365, 2022). "Philadelphia chromosome and associated chimeric oncoprotein BCR-ABL distinguish a chronic myeloid leukemia (CML)." (PMID 36501085, 2022). "The Philadelphia chromosome (BCR-ABL fusion) is a well-known example of gene fusion causing chronic myeloid leukemia (CML)." (PMID 36115852, 2022). "Ponatinib (AP24534) is a breakpoint cluster region-Abelson (BCR-ABL) inhibitor that was shown to be capable of overcoming mutation-based resistance in chronic myeloid leukemia patients." (PMID 35785164, 2022). "Chronic myelogenous leukemia (CML) is most often caused by the loss of auto-inhibitory constraint of the c-ABL kinase domain in the oncogenic fusion protein BCR-ABL." (PMID 36142231, 2022). "Recently, a number of reports have come up highlighting the concurrent presence of multiple MPN related mutations (JAK2V617F, MPL Exon 10 or CALR) with concurrent BCR-ABL positive Chronic Myeloid Leukemia." (PMID 34514582, 2022). "Breakpoint Cluster Region-Abelson kinase (BCR–Abl) is a driver oncogene that causes chronic myeloid leukemia and a subset of acute lymphoid leukemias." (PMID 33303632, 2021). "Chronic myeloid leukemia is a hematologic malignancy associated with the fusion of two genes: BCR and ABL1." (PMID 34030730, 2021). "A case study of a 56-year-old man with lymphoid blast phase chronic myeloid leukemia (CML) harboring the T315I mutation in the BCR-ABL fusion gene demonstrated that anti-CD19 CAR T cell therapy following dasatinib treatment induced complete remission." (PMID 34209505, 2021). "In a follow‐up study, the same group confirmed their previous results in an in vivo model, showing that EV transfer of BCR/ABL gene causes chronic myeloid leukemia in immunodeficient mice." (PMID 32767659, 2021). "Chronic myeloid leukemia (CML) is a hematological cancer that is predominantly caused by BCR-ABL translocations and for which targeted therapies have revolutionized cancer treatment." (PMID 34531456, 2021). "Breakpoint Cluster Region-Abelson kinase (BCR–Abl) is the driver mutation for chronic myeloid leukemia (CML) and is also found in 25% to 30% of Philadelphia chromosome–positive (Ph+) adult acute lymphoid leukemia (ALL)." (PMID 33303632, 2021). "Ponatinib is a multi-target TKI previously approved to treat chronic myeloid leukemia (CML) caused by BCR-ABL fusion." (PMID 33807778, 2021). "The BCR-ABL fusion gene is the hallmark of chronic myeloid leukemia, while the main pathogenesis of BCR-ABL-negative MPNs is over-activation of the JAK/STAT pathway." (PMID 33664283, 2021).
chronic myeloid leukemia (continued). "ABL1 on chromosome 9 undergoes mutual translocation with the BCR gene on chromosome 22 to make the Philadelphia chromosome, which is well known to cause chronic myelogenous leukemia." (PMID 33952249, 2021). "Chronic myeloid leukemia (CML) is a clonal myeloproliferative disorder that is caused by hematopoietic stem cells (HSCs) expressing the BCR-ABL fusion oncoprotein." (PMID 32661325, 2020). "Chronic myeloid leukemia (CML) is a clonal disease of pluripotent hematopoietic cells characterized by the expression of the BCR/ABL1 fusion gene, which encodes a constitutively active tyrosine kinase BCR-ABL." (PMID 31952546, 2020). "Au-nanoprobes are efficiently applied to the direct detection of the molecular hallmark of chronic myeloid leukemia, BCR-ABL fusion transcripts, allowing the discrimination between the most frequent isoforms of this genetic abnormality, e13a2 and e14a2." (PMID 33860108, 2019). "Using this new approach, the authors demonstrated robust degradation of ERα, the chronic myeloid leukemia (CML)-causative BCR–Abl fusion protein, BRD4 and PDE4 proteins in cells." (PMID 31030225, 2019). "The power of this strategy became first evident by studies of the Baltimore laboratory that modelled the effect of the chronic myeloid leukaemia (CML)-associated BCR-ABL fusion gene." (PMID 30669675, 2019). "Chronic Myeloid Leukemia (CML) is caused by the BCR-ABL gene formation encoding aberrant oncoprotein tyrosine kinase." (PMID 30487792, 2018). "Chronic myeloid leukemia is associated with a BCR/ABL oncoprotein inhibited by imatinib mesylate, the first tyrosine kinase inhibitor." (PMID 30400842, 2018). "Drugs such as the tyrosine kinase inhibitors (TKIs) developed against the BCR-ABL fusion product in chronic myeloid leukaemia (CML) and the receptor products of HER2 mutations in breast cancer have transformed the prognosis of these cancers." (PMID 29345617, 2018). "Chronic myeloid leukemia is commonly triggered by a chromosome 9 to 22 translocation that generates a fusion of the BCR (Breakpoint Cluster Region) and ABL encoding a tyrosine kinase." (PMID 29088719, 2017). "Such an addiction is neatly illustrated in chronic myeloid leukemia (CML) patients carrying BCR-ABL chimeric genes caused by translocations that can be effectively inhibited with BCR-ABL tyrosine kinase inhibitors like imatinib." (PMID 28333115, 2017). "The oncogenic BCR-ABL fusion protein disrupts ATR-dependent intra-S phase checkpoint in chronic myeloid leukemia after etoposide treatment, by causing DNA strand break formation." (PMID 28415748, 2017). "Chronic myeloid leukemia (CML) is a myeloproliferative neoplasm companied with the BCR-ABL fusion gene, which is encoded by the Philadelphia chromosome." (PMID 28283035, 2017). "For example, chimeric transcripts of the well-studied chronic myeloid leukemia causing BCR-ABL (breakpoint cluster region-Abelson protooncogene) fusion gene have been detected at low levels in the blood cells of healthy individuals as well." (PMID 28851357, 2017). "For example, secondary mutations in the BCR-ABL kinase domain that disrupt imatinib binding are common among resistant chronic myelogenous leukemia (CML) patients." (PMID 27608848, 2016). "Chronic myeloid leukemia (CML) is a myeloproliferative neoplasm associated with the presence of the BCR-ABL fusion gene encoded by the Philadelphia (Ph) chromosome." (PMID 27437766, 2016). "Chimeric breakpoint cluster region-abelson (BCR-ABL) protein (encoded by BCR-ABL oncogene) is responsible for the activity of ABL tyrosine kinase which is considered the main reason of chronic myeloid leukaemia (CML)." (PMID 27764191, 2016). "Fusion of c-Abl with BCR results in a constitutively active kinase, which is oncogenic and underlies the development of 95% of the chronic myeloid leukemia cases." (PMID 27074761, 2016).